DPP4 (dipeptidyl peptidase 4)
Diseases named in the same sentence as DPP4 in open-access papers (continued):
Sharing a sentence is not in itself a finding about the gene and the disease.
melanoma (41 papers, 2007 to 2025). A malignant, usually aggressive tumor composed of atypical, neoplastic melanocytes. "On the other hand, the absence or loss of expression of DPP4 is observed in the advanced stage of certain malignancies, including melanomas, endometrial carcinoma, and lung squamous cell carcinoma." (PMID 27936466, 2017). "Hypermethylation of the DPP4 promoter CpG island has been associated with the repression of gene expression and disease severity in human melanoma cell lines, T-cell leukemia and obese." (PMID 24736375, 2014). "It has been previously reported that loss of DPP4 immunostaining helps to discriminate malignant melanomas from deep penetrating nevi, a variant of benign melanocytic nevus and early reports of their absence in metastatic melanomas exist." (PMID 20805891, 2010). "In some metastatic melanoma samples, we also observed a subset of CD163+ TAMs in melanoma tumours co-localised with DPP4, FN1, and COX2 proteins." (PMID 38903497, 2024). "The DPP4+ASC subtype is associated with a poor prognosis in PAAD and KIRC patients, while the ADIPOQ+Adi subtype is linked to poor survival in melanoma and BRCA patients." (PMID 37454080, 2023). "In contrast, DPP4 was downregulated during the malignant transformation to melanoma cells, and DPP4 overexpression decreased the invasive ability of melanoma cells, implying an anti‐oncogenic role of DPP4 in melanoma." (PMID 37533175, 2023). "The need and importance for PACAP in neoplastic pigment cells is further strengthened by the fact that both melanoma cell lines showed weaker expression patterns at mRNA and protein levels for DPP4 in contrast to melanocytes." (PMID 34616669, 2021). "A previous report suggested a potential role of DPP-4 inhibition in CXCL10-mediated lymphocyte trafficking in melanoma B16F10-bearing mice." (PMID 34631556, 2021). "Barreira da Silva et al9 showed that in mice models with melanoma, DPP4 inhibition preserved the active form of chemokine CXCL10 which recruits T cells in tumor parenchyma." (PMID 31124302, 2019). "It is reported that DPP-4 inhibition enhanced the antitumor response to melanoma and diminished tumor growth." (PMID 29895906, 2018). "In addition to CRC, evidence points to a potential protective effect of DPP-4 inhibitors against melanoma." (PMID 39595655, 2024). "In patients with NHL, leukemia, multiple myeloma, and melanoma (more so than vitiligo), significantly decreased DPP4 activity and percentages of CD26+ lymphocytes and overall CD26+ white blood cells and lymphocytes have been observed in comparison with healthy individuals." (PMID 39001488, 2024). "DPP4 expression levels also correlate with tumor aggressiveness and invasiveness, and have been confirmed in various tumors, including renal cell carcinoma, melanoma, gynecological cancer, and hematological malignancy." (PMID 27936466, 2017). "Moreover, this signature has identified two tumor suppressor genes, DPP4 and SYK, whose downregulation has previously been implicated in melanoma development." (PMID 17611626, 2007). "CD26 (DPP4) and CALR are involved in immune modulation and cell signaling, while B7-H3 (CD276) is a prominent immune checkpoint molecule highly expressed in melanoma and other tumors, contributing to immunosuppression and tumor progression." (PMID 40805206, 2025). "The mRNA expression of DPP4, the primary degrading enzyme of PACAP, was reduced in melanocytes but elevated in both melanoma cell lines." (PMID 41465475, 2025). "As a methodology, SFD is able to reveal well-known proteins in melanoma exosomes that are immune-related and are also surface-expressed proteins, such as CD26 (DPP4), CD44, CALR, B7-H3 (CD276), CSF1, ICAM1, L1CAM, MICB, APOH, TIMP1, and CD39." (PMID 40805206, 2025). "DPP4, an enzyme that plays a role in PACAP catabolism, showed strong signals in melanocytes, but weak expression was detected in melanoma samples." (PMID 34616669, 2021).
melanoma (continued). "In addition, genes with tumor suppressor and metastasis suppressor functions (DPP4, SYK) are included in this melanoma signature." (PMID 17611626, 2007).
autoimmune disease (40 papers, 2006 to 2025). A disorder resulting from loss of function or tissue destruction of an organ or multiple organs, arising from humoral or cellular immune responses of the individual to their own tissue constituents. "In this study, we investigated the potential role of two DPP4 genetic variants, rs3788979 and rs12617656, previously implicated in cardiovascular, metabolic, and autoimmune diseases, in the context of both classic and DPP4i-associated BP." (PMID 41373842, 2025). "Clinical evidence has suggested an association between the use of DPP4 enzymatic inhibitors and several autoimmune disorders, which is summarized by Zhao group and Sahoo group in 2014 and 2021 respectively." (PMID 35309368, 2022). "A cross-sectional study observed an increased risk of several autoimmune diseases including Crohn’s disease, Hashimoto’s thyroiditis, and Psoriasis in patients on DPP4 inhibition therapy." (PMID 35309368, 2022). "Moreover, CD26 deficiency triggers M2 macrophage differentiation, and DPP4/CD26 inhibitors can decrease the risk of autoimmune disease occurrence in the course of T2D, as was shown in clinical studies." (PMID 39273582, 2024). "Similarly, the association between DPP-4 inhibitors administration and increase risk of autoimmune diseases, including inflammatory bowel disease and Hashimoto’s thyroiditis, was reported in some cohort studies." (PMID 37350750, 2023). "Therefore, upregulation of DPP4 is also associated with disease activity in human autoimmune diseases, such as rheumatoid arthritis and multiple sclerosis." (PMID 35299869, 2022). "However, most of the review articles on the role of DPP4 in autoimmune disease were focused on the association between DPP4 enzymatic inhibitors and the risk of autoimmune disease." (PMID 35309368, 2022). "Through its binding with the adenosine deaminase (ADA), this molecule can contribute to autoimmune diseases and cancers, conditions where serum DPP-4 activity and sDPP-4 levels are found altered." (PMID 40072115, 2025). "As an organ-specific autoimmune disease, very little research has addressed DPP4 expression in the thyroid tissue of HT patients." (PMID 38127960, 2024). "Since HT is an organ-specific autoimmune disease, we mainly focused on the DPP4 expression of thyroid tissue in HT patients with normal thyroid function; the DPP4 expression of peripheral blood lymphocytes was not addressed." (PMID 38127960, 2024). "Previous studies have indicated that the expression and activity of DPP4 changes in patients with several autoimmune diseases." (PMID 38127960, 2024). "DPP-4, expressed on the surface of immune cells, is a multifunctional molecule involved in the pathophysiology of autoimmune diseases." (PMID 37350750, 2023). "Many previous studies had shown that the serum concentration and activity of DPP4 changed in patients with autoimmune diseases, such as type 1 diabetes and multiple sclerosis." (PMID 37350750, 2023). "There was the different trend in DPP4 activity and concentration between different autoimmune diseases." (PMID 37350750, 2023). "This review discusses the role of DPP4 in immune system and its role in pathogenesis of different autoimmune diseases." (PMID 35309368, 2022). "Collectively, further animal and clinical studies are required to identify the exact role of DPP4 in the development of autoimmune diseases." (PMID 35309368, 2022). "Taken together, DPP4 is a promising target of autoimmune diseases although its exact mechanisms in these conditions remain elucidated." (PMID 35309368, 2022). "This review focuses on emerging evidence of DPP4 in immune regulation and attempts to build a bridge between DPP4 and autoimmune diseases." (PMID 35309368, 2022). "Contrarily, hypoglycemic agents such as GLP-1 agonists, DPP-4 inhibitors, thiazolidinediones and biguanides seem to reduce incidence of autoinflammatory and autoimmune disorders including PSO and alleviate the disease severity." (PMID 34638740, 2021).
autoimmune disease (continued). "CD26 is furthermore involved in a variety of human autoimmune diseases, and as a cell surface protease, DPP-4/CD26 plays an important role in tumor progression." (PMID 27148273, 2016). "This case suggests that the onset of an autoimmune disease may have been triggered by a "dual-trigger" mechanism involving chronic immune modulation by a DPP-4 inhibitor and acute immune stimulation from COVID-19 infection." (PMID 40895902, 2025). "DPP4, as a moonlighting protein, plays an emerging role in autoimmune disease." (PMID 41189279, 2025). "Furthermore, patients treated with DPP-4 inhibitor/metformin combination therapy had a lower risk of autoimmune disease, including IBD, compared to those receiving non-DPP-4 inhibitor/metformin regimens." (PMID 40723884, 2025). "DPP4 is broadly expressed on multiple cell types, including immune cells (T cells, B cells and monocytes), suggesting that the change in expression and activity of DPP-4 might be involved in the pathogenesis of autoimmune diseases." (PMID 37350750, 2023). "Experimental and clinical investigations suggest that DPP4 may play a dual role in the pathogenesis of autoimmune diseases and the inhibition of DPP4 results distinct outcome in different disease condition." (PMID 35309368, 2022). "Furthermore, additional evidence on the effect of low DPP4 levels on an overall reduced immune effector response is supported by the multiple DPP4 inhibitors approved for therapeutic use in different autoimmune diseases." (PMID 35413090, 2022). "Since the ADA is an enzyme involved in autoimmune diseases and cancer development, it is plausible to hypothesize that the DPP4 involvement in ADA-mediated pathways is at the basis of the elevated sDPP4 levels reported in these diseases." (PMID 36140405, 2022). "With its involvement in immune regulation and fibrosis, DPP4 may have a pivotal implication in the development of autoimmune disease." (PMID 35309368, 2022). "Moreover, increased DPP4 levels were also reported in cancer, autoimmune diseases, and neurodegenerative conditions." (PMID 36140405, 2022). "In large, prospective, population‐based cohort studies, the risk of developing an autoimmune disease was lower in patients receiving antidiabetic therapy with DPP-4 inhibitors compared to T2D patients not treated with DPP-4 inhibitors." (PMID 33995414, 2021). "However, because Ang II or DPP4 is an endogenous hormone, we must avoid autoimmune disease induced by these vaccines." (PMID 26344893, 2014). "Elevated concentrations of dipeptidyl peptidase-4/CD26 have been observed in the serum of individuals with type 1 diabetes, rheumatoid arthritis, systemic lupus erythematosus, and inflammatory bowel diseases, which suggests its involvement in the pathogenesis of autoimmune disorders." (PMID 41301757, 2025). "However, since this study focused on patients who had already developed autoimmune diseases, the impact of DPP-4 inhibitors remains unclear." (PMID 41464548, 2025). "In various settings, primarily in the context of immunomodulation and the treatment of autoimmune diseases, the dual inhibition of APN/CD13 and of the ectopeptidase DPP4/CD26 has been shown to be more effective than the inhibition of APN/CD13 alone." (PMID 36979703, 2023). "As DPP-4 plays a substantial role in the immune system, particularly in T cell function, DPP-4 has been investigated as a possible target for treating autoimmune diseases including inflammatory bowel disease." (PMID 30186247, 2018). "However, DPP4 is not a specific marker of any autoimmune disease, as its ubiquitous expression limits the potential of DPP4 as a precise biomarker." (PMID 35309368, 2022).
pancreatic cancer (40 papers, 2013 to 2025). "Certain antidiabetic agents, including SGLT2 inhibitors, GLP-1 receptor agonists, DPP-4 inhibitors, and metformin, have been implicated in reducing pancreatic cancer risk through diverse biological mechanisms." (PMID 40364115, 2025). "In this review, we have explored the effects of SGLT2 inhibitors, GLP-1 RA, DPP-4 inhibitors, and metformin on the risk of developing pancreatic cancer." (PMID 38611003, 2024). "DPP-4 inhibitors were a subject of considerable debate, particularly regarding their potential association with thyroid and pancreatic cancers." (PMID 39595655, 2024). "Though there were concerns about the use of DPP4-inhibitors with an increased risk for pancreatic cancer, subsequent studies have revealed that there are only limited effects of DPP-4 inhibitors on pancreatic cancer and general cancer risk." (PMID 34298800, 2021). "An early study analysed the FDA reports of pancreatic cancer and concluded that there was a 2.7-fold increase in the risk for pancreatic cancer with DPP-4 inhibitor use2." (PMID 29335646, 2018). "Concern regarding the association between DPP-4 inhibitor use and pancreatic cancer was raised after a review of cases reported by the FDA2." (PMID 29335646, 2018). "On the other hand, there are concerns that DPP-4 inhibitors may increase the risk of pancreatic cancer due to pancreatic expansion." (PMID 37669959, 2023). "The use of dipeptidyl peptidase-4 (DPP-4) inhibitors may be associated with pancreatic cancer and acute pancreatitis." (PMID 29335646, 2018). "Therefore, we performed a meta-analysis to assess the risk of both pancreatic cancer and acute pancreatitis associated with the use of DPP-4 inhibitors." (PMID 29335646, 2018). "Similarly, the association between DPP-4 inhibitors and pancreatic cancer remains inconclusive." (PMID 39595655, 2024). "However, there are concerns that the use of DPP-4 inhibitors may be associated with increased risk for pancreatic cancer and acute pancreatitis." (PMID 29335646, 2018). "Due to the better side effects of metformin than GLP1- RA and DPP-4 inhibitors, metformin is more favorable for use in pancreatic cancer prevention." (PMID 38611003, 2024). "In SMR analyses, ABCC8/KCNJ11, DPP4, PPARG, ETFDH, and PRKAB1 were associated with anal carcinoma, cardia cancer, and pancreatic cancer." (PMID 38504335, 2024). "So far, in cancer research, one area where DPP-4′s role has been frequently addressed is pancreatic cancer." (PMID 38611003, 2024). "Associations of ABCC8/KCNJ11, DPP4, GLP1R, GPD2, PPARG, PRKAB1, and SLC5A2 with anal carcinoma, cardia cancer, gastric cancer, HCC, ICC, pancreatic cancer, and rectum cancer were revealed in two-sample MR analyses." (PMID 38504335, 2024). "This study reviewed the recent literature on the association between pancreatic cancer risk and SGLT2 inhibitors, GLP-1 RA, DPP-4 inhibitors, and biguanides." (PMID 38611003, 2024). "Here, we report a case of pancreatic cancer in which the dipeptidyl peptidase-4 inhibitor vildagliptin induced unusual manifestations of interstitial pneumonia, possibly under the influence of Lactobacillus paraplantarum probiotic supplementation." (PMID 31908161, 2020). "There were 16 events of pancreatic cancer in the DPP-4 inhibitor group and 24 events in the control group." (PMID 29335646, 2018). "Glucagon-like peptide-1 Receptor (GLP-1R) agonists and dipeptidyl peptidase-4 (DPP-4) inhibitors have also been associated with thyroid and pancreatic cancer." (PMID 24278227, 2013). "The controversy regarding the side effects of the dpp4 inhibitors, particularly with respect to acute pancreatitis and pancreatic cancer, continues unabated." (PMID 25671081, 2013). "Regarding adverse events associated with GLP-1 RAs, current evidence does not indicate an increased risk of pancreatic cancer or acute pancreatitis, unlike DPP-4 inhibitors." (PMID 40607140, 2025).
pancreatic cancer (continued). "Evidence concerning insulin, thiazolidinediones, and sulfonylureas is less robust, while dipeptidyl peptidase-4 inhibitors may exacerbate pancreatic neoplasms." (PMID 40364115, 2025). "There are mixed data regarding the relationship between GLP-1 RA and DPP-4 inhibitors and pancreatic cancer, with some trials suggesting that they might increase the risk." (PMID 38611003, 2024). "Furthermore, ABCC8/KCNJ11, DPP4, GLP1R, PRKAB1, and GPD2 shared causal variants within anal cancer, HCC, ICC, pancreatic cancer, and rectum cancer according to the colocalization analyses." (PMID 38504335, 2024). "Notably, the authors stated that the combination of GLP‐1 RAs with DPP‐4 inhibitors may have led to an increased reporting of several tumours, including pancreatic cancer." (PMID 40988099, 2025). "So far, there is no established risk of pancreatic cancer with DPP-4 inhibitors." (PMID 38611003, 2024). "Finally, there is enough information to suggest a lack of association between the use of DPP-4 inhibitors and pancreatic cancer, but not acute pancreatitis." (PMID 29335646, 2018). "None of these reviews performed TSA to evaluate whether the results were definitive, and, more importantly, none of them evaluated the risk of pancreatic cancer associated with use of DPP-4 inhibitors." (PMID 29335646, 2018). "The association between DPP-4 inhibitors and pancreatic cancer remains inconclusive in global studies, and this uncertainty extends to Japanese populations as large Japanese cohort studies have not demonstrated a statistically significant increase in pancreatic cancer risk with DPP-4 inhibitors." (PMID 40607140, 2025). "FURIN expression was not correlated with DPP4 except for pancreatic cancer, where a negative correlation was found." (PMID 33796097, 2021).